USP28 (ubiquitin specific peptidase 28)
Diseases named in the same sentence as USP28 in open-access papers (continued):
Sharing a sentence is not in itself a finding about the gene and the disease.
cancer (continued). "MAST kinase stability is also likely regulated by ubiquitination, as MAST1 was also shown to be protected by ubiquitin-specific peptidases (USPs), USP1/USP28, and provided cisplatin resistance to cancer cells." (PMID 41237908, 2025). "From other cancers it is also reported that besides USP28, the deubiquitinases USP7, USP8, USP10 and USP11 interact with NICD and regulate NOTCH1 signaling." (PMID 40456839, 2025). "We found that the deletion of USP28 or TP53BP1 (53BP1) significantly reduced the sensitivity of several cancer cells to PLK4i treatment, mirroring the response observed in untransformed RPE1 cells." (PMID 41365927, 2025). "Recent investigations have demonstrated the efficacy of small-molecule deubiquitinase inhibitors in cell lines, further reinforcing USP28 inhibition as a promising avenue for cancer treatment." (PMID 40240356, 2025). "Known for its impact on apoptosis, DNA damage, and cell proliferation, USP28 is extensively studied in cancer where it accelerates the progression and correlates with poor prognosis in various cancers, such as glioma, colorectal, and breast cancers." (PMID 39076972, 2024). "In turn, the stabilisation of HIF-1α in hypoxia leads to activation of USP28 through SENP1-mediated USP28 deSUMOylation to further increase transcriptional activity of HIF-1 in human cancer cell lines." (PMID 39584532, 2024). "Knockout or inhibition of USP28 can effectively mitigate various cancers 12, immune system diseases 13 and neurodegenerative diseases." (PMID 39431010, 2024). "Apart from its role in cancer, the functions of USP28 beyond this context remain largely unexplored." (PMID 39076972, 2024). "A recent study reported that the inhibition of USP28 by specific inhibitors suppresses its enzymatic activity, thereby sensitizing cisplatin-resistant cancer cells to cisplatin treatment." (PMID 38498222, 2024). "MiR-500a-5p is transferred from CAF to cancer cells and subsequently promotes proliferation and metastasis by binding to ubiquitin specific peptidase 28 (USP28)." (PMID 39372872, 2024). "USP28 acts as an oncoprotein by stabilizing crucial oncoproteins in cancers, such as the transcription factor c-MYC." (PMID 38711144, 2024). "Our screening system identified USP28 as one of the potential DUBs regulating cisplatin resistance in cancers." (PMID 38498222, 2024). "Several of USP28’s substrates, such as the transcription factors c-Myc, HIF1α, and ΔNp63, the lysine-specific demethylase LSD1 and the helicase RecQ5, act as oncogenes in a variety of cancers rendering USP28 itself an essential oncogene." (PMID 38816515, 2024). "We further demonstrated that knockout of USP28 in cisplatin-resistant cancer cells suppressed cell proliferation, migration, invasion and colony formation ability." (PMID 38498222, 2024). "In support of these findings, USP28 knockdown impaired the self-renewal capacity of cancer stem cells (CSCs) derived from MMTV-Wnt1 tumors and promoted their differentiation." (PMID 39394462, 2024). "The increased miR-500a-5p via EVs downregulated ubiquitin-specific peptidase 28 (USP28), which has a role in suppressing cancer cell invasion and EMT." (PMID 38111675, 2023).
cancer (continued). "Nonetheless, our study provided a complete understanding of USP28, emphasizing the relationship between USP28 and tumor prognosis and tumor immunity across cancer types." (PMID 37450415, 2023). "Considering the aberrant expression of USP28 in various cancers, we further observed the genetic alteration status of USP28 across multiple tumor samples of TCGA cohorts." (PMID 37450415, 2023). "Currently, there is no all-encompassing investigation that thoroughly explains the impact of USP28 on tumor immune infiltration and response to immunotherapy across multiple types of cancer." (PMID 37450415, 2023). "We first analyzed the USP28 mRNA expression in the normal and cancer tissues using TCGA and GTEx datasets." (PMID 37450415, 2023). "To explore the potential prognostic value of USP28 in different types of cancer, we analyzed four prognostic indicators using Kaplan-Meier and univariate Cox regression methods." (PMID 37450415, 2023). "Further, indirect downregulation of MYC via ubiquitin–proteasome mechanisms is an excellent strategy for targeting CSCs, for instance activating SCFFBXW7 and inhibiting deubiquitinase USP28 of MYC suppresses cell proliferation in diverse cancer." (PMID 36765885, 2023). "To better analyze the immune aspects of USP28 in pan-cancer, we calculated the correlation between USP28 levels and EstimateScore, ImmuneScore, and StromalScore." (PMID 37450415, 2023). "In order to promote the accumulation of ΔNp63 in cancer, the deubiquitylate USP28 stabilizes ΔNp63 by counteracting its proteasome-mediated degradation, promoting cancer cell survival under the treatment of chemotherapy." (PMID 37182132, 2023). "Given that USP28 plays an indispensable role in different tumor progression, it is particularly important to systematically and holistically explore the role of USP28 in pan-cancer." (PMID 37450415, 2023). "In summary, our study has first confirmed that USP28 expression is a biomarker of the prognosis of cancers and can effectively predict immunotherapy response." (PMID 37450415, 2023). "The data suggested that USP28 expression is strongly related to all cancers’ four types of DNA methyltransferases." (PMID 37450415, 2023). "USP28 expression was significantly related to the prognosis of most cancers except MESO, THCA, UCS, and THYM." (PMID 37450415, 2023). "We performed the single-cell analysis of USP28 in single-cell datasets of cancer samples to understand the main cell types that express the USP28 in cancer microenvironments using the TISCH web tool." (PMID 37450415, 2023). "And mRNA expression levels of USP28 varied significantly in 22 cancer cell lines according to the CCLE database." (PMID 37450415, 2023). "We found that USP28 expression is related to many immune regulator gene expressions in many cancers, including COAD, LIHC, PAAD, PRAD, and UVM." (PMID 37450415, 2023). "Most cancers had a significant positive correlation between USP28 and neutrophil and NK T cell infiltration." (PMID 37450415, 2023). "To further elucidate the tissue-specificity of USP28 phenocopying events, we considered the prioritization scores separately for different cancer types." (PMID 37095494, 2023). "Some studies have reported that phosphorylation of USP28 was closely related to the progression of cancer." (PMID 37450415, 2023). "This study suggests USP28 was a powerful biomarker to predict response to immune checkpoint blockade therapy in pan-cancer." (PMID 37450415, 2023). "The findings revealed a robust physical association between USP28 and ZNF304, a key player in cancer metastasis." (PMID 37450415, 2023).
cancer (continued). "USP28 depletion rendered cancer cells highly sensitive to MVP inhibition by statins, which was rescued by the addition of geranyl-geranyl pyrophosphate." (PMID 37202505, 2023). "In summary, USP28 represents a promising and potential therapeutic target for cancer treatment, indicating immune infiltration and unfavorable prognosis in cancer patients." (PMID 37450415, 2023). "Our data imply that the USP28 expression level was increased in most cancer tumors and confirmed that it is highly expressed in HCC clinical samples." (PMID 37450415, 2023). "We observed that BRCA, BLCA and LUAD were the cancer types which showed the strongest signal in our prioritization score for USP28 phenocopies, with a suggestive signal in STAD." (PMID 37095494, 2023). "This provides some reference directions for further research on the role of USP28 in cancer occurrence and progression." (PMID 37450415, 2023). "The influence of USP28 on cancer prognosis and drugs that can target USP28 in carcinomas is concluded next." (PMID 36879346, 2023). "Overall, USP28 functions as a proto‐oncogene and contributes to establishing the hallmarks of cancer in cells undergoing oncogenic transformation, at least in lung." (PMID 35364627, 2022). "USP28 has been validated as an oncoprotein and therapeutic target in various cancer types, and a list of oncogenic substrates of USP28 have been reported, such as JUN, NOTCH1, CCNE, and LSD1." (PMID 36497313, 2022). "USP28 is a transcriptional target of its own substrates and, via a feed‐forward loop, increased in cancer compared with normal cells." (PMID 35364627, 2022). "USP28 levels are increased in cancer compared with in normal cells due to a feed‐forward loop, driven by increased amounts of oncogenic transcription factors such as c‐MYC and c‐JUN." (PMID 35364627, 2022). "USP28 is known to be involved in cancer-related pathways by antagonizing FBW7-dependent ubiquitination of several proteins, such as C-MYC, C-JUN, ΔNp63, and Hif-1α." (PMID 36436562, 2022). "We also conducted 3D cultures to investigate the roles of miR-500a-5p and USP28 in cancer cell proliferation." (PMID 33664871, 2021). "MiR-500a-5p was transferred from CAFs to the cancer cells, and subsequently promoted proliferation and metastasis by binding to ubiquitin-specific peptidase 28 (USP28)." (PMID 33664871, 2021). "USP28 is a targetable DUB enzyme that stabilizes crucial oncoproteins in cancer, such as the transcription factor c-MYC." (PMID 34685632, 2021). "USP28 has been shown to play complex and versatile modulatory roles in various cancers 36, through its involvement in multiple pathways that can have opposing functions." (PMID 33664871, 2021). "Publicly available expression datasets revealed an upregulation of TP63 and USP28 in cancer samples from cervix, oesophagus, head‐and‐neck or lung SCC compared to non‐transformed samples." (PMID 32128997, 2020). "Due to the role played by USP28 in various malignancies, it is identified as a potential drug target for cancer treatments." (PMID 32549302, 2020). "Consistently, we demonstrate that chronic stress increases epinephrine levels to promote tumorigenesis and cancer stem-like traits via activation of the LDHA/USP28/MYC/SLUG signaling axis in a mouse model." (PMID 30688660, 2019). "As a result, the significance of targeting USP28 for cancer treatment has been drawn more attention than before." (PMID 29415985, 2018). "As a result, the clinical significance of targeting USP28 for cancer therapy merits further exploration and demonstration." (PMID 29415985, 2018). "We discuss the major mechanisms by which USP28 is involved in the cancer-related pathways, whereby USP28 regulates physiological homeostasis of ubiquitination process, DNA-damage response, and cell cycle during genotoxic stress." (PMID 29415985, 2018). "The finding offers an alternative way to regulate HIF-1–dependent cancer pathways by targeting USP28." (PMID 29415985, 2018).
cancer (continued). "In this article, we review the emerging roles of USP28 in cancer pathways as revealed by recent studies." (PMID 29415985, 2018). "Below, we will review the mechanisms accounting for the involvement of USP28 in these pathways, hence demonstrating its significance as a therapeutic target for cancer treatment." (PMID 29415985, 2018). "In this review, we focus on discussing the specific roles of USP28 in cancer pathways, and their potential therapeutic values in cancer treatment." (PMID 29415985, 2018). "Our study demonstrated that Nickel and hypoxia exposure increased c-myc T58 phosphorylation and decreased USP28 protein levels in cancer cells, which both lead to enhanced c-myc ubiquitination and proteasomal degradation." (PMID 20046830, 2009). "Finally, to investigate the relationship between active DYRK2 -using Y382 phosphorylation at the activation loop as marker- and USP28 abundance in cancer, we analyzed CPTAC phospho-proteomic and proteomic data." (PMID 40858801, 2026). "Notably, USP28 exhibits context‐dependent roles, acting as both an oncogene and tumor suppressor across cancer types, which underscores its complex regulatory mechanisms in cellular proliferation, DNA repair, and metastasis." (PMID 40855785, 2026). "Furthermore, a substantial body of research highlights that USP28 contributes to drug resistance in cancer." (PMID 40855785, 2026). "Through the miR‐500a‐5p/ubiquitin specific peptidase 28 (USP28) axis, exosomal miR‐500a‐5p in CAFs could promote cancer cell proliferation, EMT, and metastasis." (PMID 40032646, 2025). "Several studies have identified USP28 as an oncogene in specific cancer contexts." (PMID 41365927, 2025). "As a result, USP28-deficient cancer cells exhibit attenuated responses not only to mitotic stress but also to DNA damage." (PMID 41365927, 2025). "Furthermore, the expression level of USP28 corresponded with MAST1 protein in several tested cancer cell lines." (PMID 38498222, 2024). "USP28 regulates the protein level of microtubule-associated serine/threonine kinase 1 (MAST1), a common kinase whose expression is elevated in several cisplatin-resistant cancer cells." (PMID 38498222, 2024). "Furthermore, the issue becomes more severe, given that the cancer-promoting activity of USP28 and USP25 will probably be further stimulated by the catalytic hyperactivity arising from mutation of the respective glutamates." (PMID 38816515, 2024). "In conclusion, our study demonstrates that USP28 could enhance MAST1-driven cisplatin resistance by stabilizing MAST1 protein level in cancer." (PMID 38498222, 2024). "As many FBW7 targets play significant roles in cancer, this function of USP28 is likely relevant to its genetic alteration in some cancers and could certainly contribute to its roles as both a tumor suppressor and tumor promoter." (PMID 39398482, 2024). "Thus, the USP28 gene in pan-cancer was comprehensively examined, including gene expression, genetic alteration, DNA methylation, signal pathway, protein phosphorylation, immune cell infiltration, and relationships of immune regulators." (PMID 37450415, 2023). "Moreover, we also provided information about the specific locations and frequency of alterations in the USP28 gene across different cancer types." (PMID 37450415, 2023).
cancer (continued). "It should be noted that USP28 was identified as a risk factor associated with poor prognosis in ACC and PCPG, as it was significantly correlated with four different prognostic survival indicators in these cancers." (PMID 37450415, 2023). "Hence, the prognostic role of USP28 in predicting cancer prognosis suggests that further investigation is needed better to understand the function of USP28 in cancer cells." (PMID 37450415, 2023). "While further experiments are required to reveal the full complexity of cancer-relevant pathways controlled by USP28 and SREBP2, the results provided by our study add an additional layer to the regulation of SREBP2 activity and open novel translational avenues for the treatment of squamous tumours." (PMID 37202505, 2023). "Furthermore, we evaluated the expression status of USP28 in various cancers and normal tissues by TCGA and GTEx databases." (PMID 37450415, 2023). "We first found that USP28 expression was strongly correlated with CNV in some cancers." (PMID 37450415, 2023). "Moreover, according to the TIMER, MCPCOUNTER, and QUANTISEQ algorithms, we observed a significant positive correlation between USP28 expression and neutrophil’s estimated infiltration value in the pan-cancer analysis." (PMID 37450415, 2023). "We concluded that USP28 could potentially be a prognostic marker and a novel target for tumor immunity in different cancers." (PMID 37450415, 2023). "The results suggest that USP28 expression levels may serve as a predictive biomarker for the efficacy of immune checkpoint inhibitors in the corresponding cancers." (PMID 37450415, 2023). "USP28 expression was significantly correlated with the five MMR genes in all cancers." (PMID 37450415, 2023). "We analyzed the genomic alterations of USP28 in various cancers using the cBioPortal dataset." (PMID 37450415, 2023). "We also analyzed the relationship between USP28 expression and neoantigens in pan-cancer." (PMID 37450415, 2023). "The results revealed that USP28 was highly expressed in most cancers, including LIHC." (PMID 37450415, 2023). "In addition, multiple algorithm results showed that the expression of USP28 was positively correlated with the infiltration levels of CAFs, B cells, and macrophages in most cancers." (PMID 37450415, 2023). "Next, we investigated the potential of USP28 as a predictor of cancer immunotherapy response." (PMID 37450415, 2023). "Our study evaluated the relationship between USP28 and clinical prognosis in cancer patients." (PMID 37450415, 2023). "Taken together, these results suggest that USP28 could potentially modulate tumorigenesis and cancer progression by exerting control over the epigenetic state of cancer cells." (PMID 37450415, 2023). "However, even though we incorporated some datasets to analyze the clinical significance of USP28 in pan-cancer analysis for the first time, this investigation still had several limitations." (PMID 37450415, 2023). "USP28 was shown to control the stability of a number of cancer-relevant proteins, most notably MYC." (PMID 37202505, 2023). "In addition to its significance in oncogenic functions attracting the attention of researchers, the anti-carcinoma effects of USP28 have also attracted attention." (PMID 36879346, 2023). "USP28 was expressed in many cancers and had different biological mechanisms." (PMID 35299740, 2022).